Y_RNA (Y RNA )
Gene: Miscellaneous RNA gene on chromosome 10 (31,756,042 to 31,756,136, reverse strand). Ensembl gene ENSG00000222412.
Homologues: Orthologues: chimpanzee Y_RNA (99% identical). Paralogues in human: RNY4 (87% identical), RNY4P6 (86% identical), RNY4P13 (84% identical), RNY4P37 (84% identical), RNY4P7 (84% identical), Y_RNA (84% identical), RNY4P10 (83% identical), RNY4P19 (83% identical), RNY4P3 (83% identical), Y_RNA (83% identical), RNY4P14 (82% identical), RNY4P23 (82% identical), and 93 more.